GATA6-AS1 (GATA6 antisense RNA 1)
Synonyms: locus5689; BM742401
Gene: Long non-coding RNA gene on chromosome 18 (22,087,583 to 22,169,878, reverse strand). Ensembl gene ENSG00000266010.
Pathways (Reactome):
Developmental Biology: Formation of definitive endoderm
Diseases named in the same sentence as GATA6-AS1 in open-access papers:
GATA6-AS1 is named in the same sentence as 4 diseases in open-access papers, as found by Europe PMC text mining. Sharing a sentence is not in itself a finding about the gene and the disease. The quoted sentences say what the papers report.
tumor (2 papers, 2020). "We also identified the lncRNAs GATA6‐AS1 (GATA6 Antisense RNA 1) and HMGA2 (High Mobility Group AT‐Hook 2) within term C. In our data, GATA6‐AS1 was significantly downregulated in IVL tumor samples (P = .0246)." (PMID 32372565, 2020).
cancer (1 paper, 2021). A tumor composed of atypical neoplastic, often pleomorphic cells that invade other tissues. "GATA6 antisense RNA 1 (GATA6-AS1) has been reported to be involved in the progression of several types of cancer." (PMID 34429758, 2021).
GATA6-AS1 also shares sentences with these, for which no sentence is quoted: gastric cancer (1 paper); myeloma (1).